SGPL1 (sphingosine-1-phosphate lyase 1)
Diseases named in the same sentence as SGPL1 in open-access papers (continued):
Sharing a sentence is not in itself a finding about the gene and the disease.
atherosclerosis (1 paper, 2013). A disease characterized by the build-up of fatty material and calcium deposition in the arterial wall resulting in partial or complete occlusion of the arterial lumen. "As S1P levels are tightly controlled by S1P lyase, we investigated the impact of hematopoietic S1P lyase (Sgpl1−/−) deficiency on leukocyte subsets relevant to atherosclerosis." (PMID 23700419, 2013).
Blindness (1 paper, 2021). Blindness is the condition of lacking visual perception defined as a profound reduction in visual perception. "Our analysis of neurodevelopment was hampered by the inability of the operator to maintain blindness to genotype because untreated Sgpl1-KO pups are runted, which becomes obvious after the first week of life." (PMID 33755599, 2021).
bone cancer (1 paper, 2020). A primary or metastatic malignant neoplasm affecting the bone or articular cartilage. "That is a contradiction to our previous data in breast and bone cancer and to other cancer studies focusing on the SGPL1 in cancer progression." (PMID 31455837, 2020).
bronchiolitis (1 paper, 2025). Inflammation of the bronchioles characterized by swelling of the bronchioles and mucus accumulation. "The patient with SGPL1-deficiency required multiple hospitalizations due to infections, including suspected cytomegalovirus colitis, RSV bronchiolitis, and episodes of central line-associated coagulase-negative staphylococcal sepsis." (PMID 41288825, 2025).
Charcot-Marie-Tooth disease (1 paper, 2023). An inherited degenerative disorder involving the peripheral nerves. "SGPL1 deficiency causes an AR, axonal form of Charcot-Marie-Tooth disease (CMT)." (PMID 36875645, 2023).
cognitive deficits (1 paper, 2022). "Developmental neural-targeted Sgpl1 ablation (Sgpl1flox/flox/NES mouse) caused massive S1P accumulation in the brain, altered presynaptic architecture, and induced cognitive deficits." (PMID 35769463, 2022).
experimental autoimmune encephalomyelitis (1 paper, 2013). An autoimmune demyelinating disease of the central nervous system that is produced experimentally in animals by the injection of homogenized brain or spinal cord in Freund's adjuvant. "The therapeutic relevance of Sgpl1 is demonstrated by the fact that the inducible KO mice are protected in experimental autoimmune encephalomyelitis (EAE)." (PMID 23544080, 2013).
focal segmental glomerulosclerosis (1 paper, 2022). A renal disorder characterized by sclerotic lesions in the glomeruli. "Increased ceramide levels in podocytes from aCDase-knockout mice and in steroid-resistant NS patients with mutations of SGPL1 led to foot process effacement (FPE) indicative of NS and focal segmental glomerulosclerosis (FSGS)." (PMID 35409370, 2022).
glioblastoma (1 paper, 2016). The most malignant astrocytic tumor (WHO grade IV). "Beside glioblastoma patient samples, we isolated glioblastoma cells from freshly resected tumor tissue of three different patients and analyzed the expression of S1P1-5, SphK1 and 2, SGPP1 and 2 as well as SGPL1 by quantitative RT-PCR." (PMID 26887055, 2016).
Hyperkeratosis (1 paper, 2022). Hyperkeratosis is a histopathological term defining a thickened stratum corneum and may be present in many different skin conditions, with many possible overlaps. "Though, the pathology on these tamoxifen-induced Sgpl1 knock-out mice was very mild compared to ours: the H&E skin section presented as hyperkeratosis was only revealed with two layers of epidermal keratinocytes it is the figure of the cited paper." (PMID 35769463, 2022). "Therefore, Sgpl1 inhibition or S1P administration can attenuate hyperkeratosis during psoriasis vulgaris progression and serve as a putative method of treating this disease." (PMID 35769463, 2022).
Infertility (1 paper, 2021). "Therefore, the mechanism of SGPL1 in mice provides a potential implication for the diagnosis and treatment of clinical infertility." (PMID 34083520, 2021). "Sgpl1-knockout mice fail to develop germ cells, resulting in infertility." (PMID 34083520, 2021).
insulinoma (1 paper, 2024). "Also, in INS1E rat insulinoma cells, knockdown of Sgpl1 increased [Ca2+]i, measured with the Ca2+ sensor Case12, while Sgpl1 overexpression slightly reduced [Ca2+]i." (PMID 39392480, 2024).
invasive breast carcinoma (1 paper, 2018). A carcinoma that infiltrates the breast parenchyma. "Both invasive breast cancer cells displayed only small spots of aggregated SGPL1 proteins." (PMID 29718989, 2018).
metastatic tumor (1 paper, 2018). "This hypothesis is strengthened by the finding that SGPL1 is significantly downregulated in metastatic tumor tissues compared to primary tumors from the same patients." (PMID 29718989, 2018).
neural tube defect (1 paper, 2014). A congenital defect characterized by failure of the neural tube to close completely; this results in the presence of openings in the brain or spinal cord. "We examined the incidence of neural tube defects and weight changes of fetus and placenta, as well as the gene expression of LASS5 (in maternal liver and fetus), Sphk1, Sphk2, Sgpl1, and Sgpp1 in the maternal liver, uterus, fetus, and placenta." (PMID 25383881, 2014).
Neurodevelopmental delay (1 paper, 2021). "We infer from these results that neurological impairment is manifest in Sgpl1-KO mice as early as the first weeks of life and that immediate treatment after birth with AAV-SPL prevents neurodevelopmental delay." (PMID 33755599, 2021).
Osteopenia (1 paper, 2019). Osteopenia is a term to define bone density that is not normal but also not as low as osteoporosis. "Moreover, since S1pr2-deficient mice, similar to S1pr3-deficient mice were found to display osteopenia, it might be informative to combine the S1P2-deficiency with mouse models of increased S1P levels (including Sgpl1-deficient mice) in future experiments." (PMID 31314788, 2019).
rectal cancer (1 paper, 2025). A primary or metastatic malignant neoplasm that affects the rectum. "We found that in the TCGA colon and rectal cancer data, the RNA expression of SPHK1 and SGPL1 were positively correlated with the extent of macrophage infiltration in the tumor microenvironment, but not with T cells or B cells." (PMID 40589755, 2025).
schizophrenia (1 paper, 2020). A major psychotic disorder characterized by abnormalities in the perception or expression of reality. "In the BA8, the transcript expression level of SGPL1 or PLPP3 was also significantly higher in the schizophrenia group than in the controls." (PMID 32346731, 2020). "Therefore, a higher expression of SGPL1 and PLPP3 in the BA8 of patients with schizophrenia may have stemmed from a lower RIN or associated phenomena." (PMID 32346731, 2020). "We further examined the correlation of SGPL1 or PLPP3 expression level with RNA integrity number (RIN), as the RIN in the corpus callosum of patients with schizophrenia differed significantly from that of the controls." (PMID 32346731, 2020). "The expression levels of Sphingosine-1-Phosphate Lyase 1 (SGPL1) and Phospholipid Phosphatase 3 (PLPP3) showed a significantly higher (P = .006) and an elevated trend (P = .09), respectively, in the corpus callosum of patients with schizophrenia compared with controls." (PMID 32346731, 2020). "This suggests that, rather than by increased SGPL1 expression, an S1P-degrading process augmented by elevated PLPP3 expression may, at least in part, be responsible for the lowered S1P content in the corpus callosum of patients with schizophrenia." (PMID 32346731, 2020).
tauopathies (1 paper, 2020). "Further studies into the molecular mechanisms by which SGPL1 deficiency and/or S1P accumulation in the brain affect tau hyperphosphorylation, clearance and pathology could therefore be of great interest to the field of tauopathies." (PMID 32998447, 2020). "Hence, although sites relevant to tauopathies including AD are hyperphosphorylated, we feel that, due to the multitude of phosphorylation sites in tau and the complexity of this phenomenon, more studies are needed to finally understand the function of SGPL1 in tauopathies." (PMID 32998447, 2020).
cancer (29 papers, 2014 to 2025). A tumor composed of atypical neoplastic, often pleomorphic cells that invade other tissues. "Of note, the gene SGPL1 maps to a region prone to mutations in several human cancers and also in S1P-lyase insufficiency syndrome (SPLIS) characterized by several symptoms, including peripheral and central neurological defects." (PMID 36902011, 2023). "Our results indicate that HIF‐1, generally known to orchestrate cellular adaptation to low oxygen, thus promoting malignancy of cancer cells, also mediates aerobic glycolysis in SGPL1‐deficient MEFs." (PMID 35973936, 2022). "In future studies, the role of SGPL1 mutations for the patient outcome and the effectiveness of an anti-cancer treatment should be further evaluated." (PMID 31455837, 2020). "In the SK2-overexpressing cancer cell lines, nuclear S1P was shown to directly interact and thus inhibit HDACs1 and 2 while in SGPL1-deficient MEFs a reduced expression of HDACs1, 2, and 3 was reported." (PMID 32998447, 2020). "In humans, SGPL1 is encoded by SGPL1, which is prone to mutations found in several cancers and also in a variety of pathologies that include peripheral and central neurological defects, collectively referred to as S1P-lyase insufficiency syndrome (SPLIS), which can lead to early infant death." (PMID 37508508, 2023). "Intriguingly, the human gene encoding SGPL1 maps to a region that is prone to mutations in cancer." (PMID 35973936, 2022). "Moreover, high concentrations of S1P or deficiencies in S1P degradation by SGPL1 have been associated with cancer cell progression, directed chemoattraction and promotion of chemo-resistance mechanism." (PMID 33947373, 2021). "Together with our data, these observations suggest that increased SPHK1 and decreased SGPL1 or SGPP2 may be a relatively common pathogenic mechanism that could also be involved with therapy resistance in several cancer types." (PMID 26493335, 2015). "These proteins, including AHCYL1, APLP2, CTNN1D, EIF2B1, LGALS1, and SGPL1, play vital roles in maintaining cellular functions such as cell adhesion, protein synthesis, and lipid metabolism, which are often perturbed in cancer cells." (PMID 40090465, 2025). "We have reported recently that depletion of SGPL1 in MEFs affects sphingolipid metabolism in a way that is characteristic of cancer cells." (PMID 35973936, 2022). "Obviously, cancer cells are able to escape cell cycle arrest and Ki-67 attenuation under SGPL1 knockout." (PMID 34073605, 2021). "To confrim the in vitro anticancer activity of the two lead compounds against cancer cells with a high or poor endogenous expression of SGPL1, we used RMG-I and ES-2 cells." (PMID 31123329, 2019). "SGPL1 is responsible for the irreversible cleavage of S1P into hexadecenal and ethanolamine phosphate, but there has been little investigation of SGPL1 in human cancers." (PMID 26493335, 2015). "Conversely, in SGPL1-deficient fibroblasts, glycolysis was uncoupled from the TCA cycle and shifted to aerobic glycolysis, promoting cell growth similar to that often described in cancer cells." (PMID 36902011, 2023). "In the present study we asked whether SGPL1 depletion also affects other metabolic pathways that, like sphingolipid metabolism, are closely connected to the development and progression of cancer." (PMID 35973936, 2022). "The expression of SPHK2 and SGPL1 were downregulated in cancer compared to normal tissue." (PMID 32630814, 2020). "SGPL1 was expected to be a therapeutic target in some cancers, suggesting that these lead molecules might be promising candidates; however, their mechanisms of action still remain unexplained." (PMID 31123329, 2019). "Nevertheless our data demonstrates that S1P production controlled by SPHK1 and SGPL1 are key determinants of cytotoxic drug resistance and that decreasing S1P production in cancer cells could lead to increased cytotoxic sensitivity." (PMID 26493335, 2015).
cancer (continued). "However, other studies showed a different mechanism of SGPL1 involvement in carcinogenesis and revealed that SGPL1 knockout also promoted the transformation of normal mouse colon epithelium into cancer cells and provoked the immediate appearance of neoplastic tumors." (PMID 37108361, 2023). "Notably, we found that hnRNP H1 downregulation did not influence the expression of SGPL1 mRNA in non-tumorous cells, suggesting that hnRNP H1-induced upregulation of SGPL1 mRNA was cancer-specific and might be a new target of cancer therapy." (PMID 32630435, 2020). "Furthermore, the S1P stimulated migration of these cancer cells could be diminished by restoring the SGPL1 activity and localization." (PMID 31455837, 2020). "The gene expression of sphingosine-1-phosphate lyase 1 (SGPL1) which executes the final decisive step of the sphingolipid breakdown pathway, mediating the irreversible cleavage of the lipid-signaling molecule S1P, was also significantly increased in cancer." (PMID 29731990, 2018).
tumor (28 papers, 2009 to 2025). "Strikingly, Sgpl1-deficient BMDMs had improved anti-tumor activity, suggesting that SGPL1 and S1P metabolism are potential therapeutic targets to improve anti-tumor immunity." (PMID 37388918, 2023). "Consistently, we found an increase of glucose uptake and a shift to aerobic glycolysis in SGPL1‐deficient cells, two candidates of tumor progression." (PMID 35973936, 2022). "Hereby, immune cell specific SGPL1 ablation caused massive immune cell infiltration, delayed tumor formation, and a mix between the previously observed STAT3 pattern and immunosuppressive marker expression." (PMID 35163211, 2022). "The influence of the plasma membrane association on tumor physiology was estimated in two experiments: a) stimulation of the migration by the application of extracellular S1P and b) restoration of the SGPL1 function by a stable overexpression of the natural SGPL1 variant." (PMID 29718989, 2018). "Previous studies have largely focused on tumor cell-intrinsic effects, such as targeting SPHK1 to inhibit S1P synthesis or enhancing SGPL1 to degrade S1P, with the aim of suppressing tumor proliferation." (PMID 40589755, 2025). "Most notably, we identified specific enzyme–metabolite interactions (like the SGPL1 enzyme with sphingolipids) that help the virus weaken cells’ defenses while promoting tumor growth." (PMID 40906080, 2025). "Through its irreversible S1P degradation activity, the endoplasmic reticulum (ER) membrane-localized enzyme sphingosine-1-phosphate lyase (SGPL1) plays a critical part in preventing S1P overstimulation in tumor cells." (PMID 38922530, 2024). "We found that tumor macrophages induce the sphingosine-1-phospate-degrading enzyme SGPL1, which dampened their inflammatory phenotype and anti-tumor function in vivo." (PMID 37388918, 2023). "Our proteomic data revealed that TAMs upregulate SGPL1, which we found inhibited their anti-tumor activity." (PMID 37388918, 2023). "They identified significant phenotype alterations in tumor-infiltrating immune cells, including SGPL1 upregulation in macrophages and AFAP1L2 in T cells." (PMID 37388918, 2023). "Taken together, our data indicate that macrophages upregulate SGPL1 in tumors, which in a mouse model reduced their inflammatory response, and impaired their anti-tumor activity." (PMID 37388918, 2023). "To test this, we mixed MC38 tumor cells together with Sgpl1-edited BMDMs in a 1:1 ratio and co-injected them into wild-type recipient mice." (PMID 37388918, 2023). "S1P‐lyase (SGPL1) irreversibly cleaves S1P in the final step of sphingolipid catabolism and exhibits remarkably decreased enzymatic activity in tumor samples." (PMID 35973936, 2022). "The endoplasmic reticulum (ER) membrane localized enzyme sphingosine-1-phosphate lyase (SGPL1) has a key role in prevention of S1P overstimulation in tumor cells by its irreversible S1P degradation activity." (PMID 31455837, 2020). "Protein expression analysis by western blotting verified a significantly boosted SGPL1 protein content in all tumor cell lines especially in the RMA cell lines RH-30 and HA-OH1 compared to the non-tumorigenic HSkM control." (PMID 31455837, 2020). "This confirms that knockout of Sgpl1 increases IL-12 production, which drives anti-tumor immunity." (PMID 37388918, 2023). "As such, a safer approach might be to target SGPL1 specifically in tumor macrophages, for example, by using macrophage-targeting nanoparticles." (PMID 37388918, 2023). "After 1 week, Sgpl1-edited BMDMs significantly inhibited tumor growth compared with control BMDMs." (PMID 37388918, 2023). "However, intriguingly, in tumor-free colon tissue of SGPL1 knockout mice in disease, Ki-67 staining completely vanished in all crypt cells." (PMID 34073605, 2021). "SGPL1 knockout tumor tissue showed areas of low and high FOXO3 staining." (PMID 34073605, 2021).